OR4C45 (olfactory receptor family 4 subfamily C member 45 (gene/pseudogene))
Description:
Odorant receptor.
Gene: Protein-coding gene on chromosome 11 (50,032,874 to 50,033,794, forward strand). Ensembl gene ENSG00000260811.
Subcellular location: Cell membrane
Pathways (Reactome):
Sensory Perception: Expression and translocation of olfactory receptors
Genetic constraint (gnomAD): Missense variants: 103 observed, 118.13 expected, observed/expected ratio (o/e) 0.87, 90% interval 0.74 to 1.03. Synonymous variants: 33 observed, 45.08 expected, observed/expected ratio (o/e) 0.73, 90% interval 0.55 to 0.98.
Homologues: Orthologues: rat Or4c52 (78% identical), mouse Or4c126 (77% identical), mouse Or4c52 (77% identical), rat Or4c52 (77% identical), rat Or4c127 (75% identical), mouse Or4c127 (74% identical). Paralogues in human: OR4C46 (62% identical), OR4C12 (60% identical), OR4C5 (60% identical), OR4C13 (59% identical), OR4A15 (58% identical), OR4C15 (57% identical), OR4C6 (57% identical), OR4A5 (56% identical), OR4A47 (56% identical), OR4C3 (55% identical), OR4B1 (54% identical), OR4S2 (54% identical), and 116 more.